GPX3 (glutathione peroxidase 3)
Diseases named in the same sentence as GPX3 in open-access papers (continued):
Sharing a sentence is not in itself a finding about the gene and the disease.
breast carcinoma (continued). "Moreover, two potential mechanisms responsible for GPX3 downregulation in breast cancer, including hypermethylation of GPX3 promoter and release of hsa-miR-324-5p inhibition." (PMID 32782436, 2020). "All these findings showed that GPX3 was negatively correlated with progression of breast cancer and might function as a tumor suppressor in breast cancer." (PMID 32782436, 2020). "We intended to ascertain if GPX3 affects metastasis of breast cancer." (PMID 32782436, 2020). "Thus, we preliminarily evaluated the promoter methylation level of GPX3 in breast cancer, and found that it was significantly upregulated in breast cancer compared with normal breast tissues." (PMID 32782436, 2020). "Finally, we preliminarily probed the possible molecular mechanisms that accounted for GPX3 downregulation in breast cancer." (PMID 32782436, 2020). "Firstly, we explored the effect of GPX3 on growth of breast cancer cells." (PMID 32782436, 2020). "Our results suggest that epigenetic regulation of GPX3 occurred widely in breast cancer tissues compared to normal breast tissues and this may be due to GPX3 promoter hypermethylation in breast cancer cells and not in normal breast tissues." (PMID 24790704, 2014). "Our study indicates that in addition to an important role in development of these cancers, GPX3 may also play a role in the development and progression of breast cancer." (PMID 24278290, 2013). "Five SNPs, GPX3 rs2070593 (p=0.002), GPX4 rs2074451 (p=0.046), SELS rs9874 (p=0.029), TXNRD1 rs17202060 (p=0.007) and TXNRD2 rs7322262 (p=0.025), significantly interacted with DOBS to alter breast cancer risk." (PMID 24278290, 2013). "Four SNPs (GPX3 rs2070593, rsGPX4 rs2074451, SELS rs9874, and TXNRD1 rs17202060) significantly interacted with dietary oxidative balance score after adjustment for multiple comparisons to alter breast cancer risk." (PMID 24278290, 2013). "Studies indicate that GPX3 may serve as a diagnostic biomarker for oxidative stress-induced encephalitis; furthermore, GPX4, another family member, regulates reactive oxygen species (ROS) levels in breast cancer cells to resist ferroptosis." (PMID 41170198, 2025). "Moreover, increased expression of GPX3 could also suppressed invasion of breast cancer cells, which was detected by transwell invasion assay." (PMID 32782436, 2020). "For example, the inactivation of GPx3 may contribute to the progression of breast cancer." (PMID 32571353, 2020). "Moreover, we also elucidate that promoter hypermethylation and miR-324-5p-mediated suppression may be two potential mechanisms responsible for GPX3 downregulation in breast cancer." (PMID 32782436, 2020). "So the delivery of GPx3 to breast tumor tissues through hiPSC-MSCs or other methods may promote its expression, and reduce the influence of ROS on the progression of breast cancer accordingly, finally achieve the goal of treating breast cancer." (PMID 32571353, 2020). "Thus, overexpressed miR-324-4p might be another mechanism that accounted for GPX3 downregulation in breast cancer." (PMID 32782436, 2020). "Some reports showed that genetic variations in some selenoproteins, such as GPX1, GPX3, GPX4, SELENOS, and TXNRD1, are correlated to breast cancer development." (PMID 35158912, 2022). "Four GPXs family genes had the significant ability to distinguish breast cancer tissues from normal breast tissues, including GPX2, GPX3, GPX4 and GPX8." (PMID 32782436, 2020). "The results revealed that GPX1, GPX2, GPX3 and GPX4 protein levels were markedly decreased in breast cancer when compared with normal controls." (PMID 32782436, 2020). "A blinded set of plasmas from 21 breast cancer patients (age = 36 - 78, cancer grade = O - IV) and 21 normal healthy women (age = 17 - 49) were tested to determine individual levels of BTD and GPX3 by Western blots." (PMID 20346108, 2010).
breast carcinoma (continued). "Four of the top 20 genes are upregulated in cancer stem cells, including Id3 in cancer stem cells of a mouse mammary tumor model and ID3 in intrahepatic cholangiocarcinoma tumors; MGST1 in human pancreatic cancer stem cells; and GPX3 and GSN in quiescent colon cancer stem cells." (PMID 36142331, 2022). "Breast cancer patients with higher expression of GPX2, GPX3 or GPX5 had better prognosis." (PMID 32782436, 2020). "The present results showed that GPX3 methylation was detected in breast carcinoma tissues and not in normal breast tissues." (PMID 24790704, 2014). "We found that the level of GPX3 mRNA expression in normal breast tissues was significantly higher than that in breast carcinoma tissue samples of non-IBC and IBC (P = 0.001 and P < 0.001, resp)." (PMID 24790704, 2014). "Statistical analysis, using the Chi-square test, revealed that normal breast tissues express significantly high level of GPX3 protein compared to breast carcinoma tissues of non-IBC and IBC patients (P = 0.001 and P < 0.001, resp)." (PMID 24790704, 2014). "Although the role of GPX3 has been studied in different cancer types, its role in breast cancer and its epigenetic regulation have not yet been investigated." (PMID 24790704, 2014). "However, the function and mechanism of GPX3 in breast cancer have not been reported and need to be further elucidated." (PMID 32782436, 2020). "However, the medians of CD14 and GPX3 in breast cancer patients did not have significant difference with the normal controls (p > 0.05)." (PMID 20346108, 2010). "Similarly, for early breast cancer, the best three k-gene discriminators are {GPR109B, PCOLCE2, PCSK5}, {PCSK5+COL10A1, FERMT2+SPINT2, MAOA+IGJ}, {COL1A1+PCSK5+TF, GPX3+COL1A1+SPINT2, GPX3+FAP+TMEM97}, and {RRM2+COL1A1+GPR109B+IGJ, RRM2+COL1A1+GPR109B+IGJ, RRM2+COL1A1+GPR109B+SPINT2}, respectively." (PMID 21060876, 2010). "Moreover, we speculated that a combination of three markers of Se status, namely total-Se, activity of the extracellular selenoprotein glutathione peroxidase-3 (GPx3) and concentration of SELENOP provides more accurate prognostic information than a single marker alone in breast cancer." (PMID 40435558, 2025). "We analyzed the level of expression of GPX3 in normal breast tissues obtained from healthy volunteers during mammoplasty, and non-IBC and IBC breast carcinoma tissues." (PMID 24790704, 2014). "Overall, considering both the CCLE and LINCS datasets, eight selenoproteins were overexpressed (DIO2, GPX1, GPX4, SELENOI, SELENON, SELENOS, TXNRD1 and TXNRD3) and five were down-expressed (DIO1, GPX2, GPX3, SELENOP and SELENOW) in TNBC compared to all other “non-TNBC” breast cancer subtypes." (PMID 35158912, 2022).
lung carcinoma (24 papers, 2013 to 2025). "In lung cancer specifically, GPX3 expression is silenced via methylation, a phenomenon linked to metastasis and chemotherapy resistance in LUAD." (PMID 41170198, 2025). "The main purpose of the present study was to examine the mechanism(s) underlying GPx3-mediated tumor suppression in lung cancer cells." (PMID 30260967, 2018). "Multivariate logistic regression analysis was done to further test the association of BCHE and GPX3 with the risk of lung cancer." (PMID 28837649, 2017). "With the selected proteins BCHE and GPx3, multivariate logistic regression analysis was done to further test the association of biomarkers with the risk of lung cancer." (PMID 28837649, 2017). "Similarly, there is a possibility that the GPx3 levels have elevated to resist the increased oxidative stress caused by recurrence of lung cancer patient during postoperative period." (PMID 33255360, 2020). "Thus, overexpression of GPx3 in lung cancer cells causes an increased percentage of cells to stall in the S and G2/M phases." (PMID 30260967, 2018). "Secondly, GPx3 was shown to be effective in slowing down the proliferation, migration, and invasion of lung cancer cells under oxidative stress and in significantly reducing the production of ROS." (PMID 38732573, 2024). "GPX3 serum levels were employed as biomarker for the recurrence of lung cancer after complete resection." (PMID 37087463, 2023). "A separate study using various human lung cancer cell lines found that GCs can increase the gene expression of Gpx3, and gene analysis techniques identified a pair of glucocorticoid response elements (GREs) in the downstream regulatory region." (PMID 37033382, 2023). "Nevertheless, GPX2 and GPX3 are engaged in the body’s metabolic mechanism for maintaining glutathione levels, which can successfully prevent lung cancer." (PMID 37955007, 2023). "A study using lung cancer cell lines found that GCs bind a pair of glucocorticoid response elements (GREs) located in the downstream regulatory region of the Gpx3 gene, thereby increasing expression." (PMID 36830084, 2023). "GR has been shown to regulate glutathione synthesis and Gpx3 expression in lung cancer cells, highlighting its ability to contribute to antioxidant responses." (PMID 35479312, 2022). "It has been reported that in lung cancer cells, GPX3, as a redox regulator, inhibits the production of ROS and blocks the G2/M phase of the cell cycle, thereby inhibiting the proliferation of lung cancer cells." (PMID 35340708, 2022). "GPX3, a scavenger of reactive oxygen species, is known to inhibit the growth, invasion, and migration of various lung cancer cells, including h157, h460, h1299, h1650 h1975, and A549." (PMID 35354498, 2022). "Consistent with our observation of its downregulation, promoter hypermethylation and downregulation of GPX3 in melanoma, stomach, head and neck, cervical and lung cancers suggest that GPX3 serves as a tumor suppressor in these cancers." (PMID 33828156, 2021). "A previous retrospective study reported the downregulation of GPx3 in lung cancer patients who underwent surgery; therefore, serum GPx3 was proposed as a biomarker of early-stage lung cancer." (PMID 33255360, 2020). "Accordingly, we conducted this prospective study to examine the usefulness of serum GPx3 as a biomarker of recurrence after lung cancer surgery at a single institution." (PMID 33255360, 2020). "We aimed to examine the usefulness of serum glutathione peroxidase 3 (GPx3) as a biomarker of lung cancer recurrence after complete resection." (PMID 33255360, 2020). "For example, it was shown that re-expression of GPx3 in lung cancer cell lines suppressed proliferation, migration and invasion by inhibiting the ROS-mediated activation of NF-kB signaling." (PMID 32781581, 2020). "In cell culture studies, GPx3 overexpression similarly inhibits proliferation and invasion of lung cancer, HCC, and esophageal squamous cell carcinoma cells." (PMID 32781581, 2020).
lung carcinoma (continued). "The results showed that GPx3 effectively suppressed proliferation, migration, and invasion of lung cancer cells under oxidative stress." (PMID 30260967, 2018). "We previously reported that plasma GPx3 is a bio-marker of lung cancer as levels in patients with lung cancer are lower than those in normal individuals." (PMID 30260967, 2018). "According the result of this study, GPx3 expression in lung cancer patients is lower, both in the cells (or tissue) of patient lungs and in the patient plasmas, than that in healthy controls." (PMID 30260967, 2018). "We next examined how GPx3 inhibits the proliferation of lung cancer cells using FACS analysis to measure changes in cell cycle distribution." (PMID 30260967, 2018). "We also found that inactivation of cyclin B1 significantly suppressed by nuclear factor-κB(NF-κB) inactivation in lung cancer cells was dependent on GPx3 expression." (PMID 30260967, 2018). "We found that overexpression of GPx3 significantly inhibited the proliferation, migration, and invasion of lung cancer cells and arrested growth at the G2/M phase." (PMID 30260967, 2018). "Recently, we demonstrated glucocorticoid receptor-mediated upregulation of GPx3 in lung cancer cells." (PMID 30260967, 2018). "We found that GPx3 overexpression significantly reduced nuclear translocation of NF-κB upon oxidative stress, thereby inhibiting cyclin B1 expression in lung cancer cells." (PMID 30260967, 2018). "We also found that GPx3 expression after oxidative stress significantly suppressed the proliferation, migration and invasion of lung cancer cells and specifically arrested cells in the G2/M phase of the cell cycle." (PMID 30260967, 2018). "The result was that they do statistically significantly decrease the risk of lung cancer: for BCHE, Exp(β) = 0.571 (p < 0.05) and for GPx3 Exp(β) = 0.803 (p < 0.01)." (PMID 28837649, 2017). "In a previous study, we found that the mean serum GPX3 levels were lower in the lung cancer group compared to control group." (PMID 28837649, 2017). "This test showed that both biomarkers statistically significantly decrease the risk of lung cancer: for BCHE, Exp(β) = 0.525 (p < 0.05) and for GPx3 Exp(β) = 0.735 (p = 0.059)." (PMID 28837649, 2017). "However, recent studies reveal a paradoxical role for GPX3 in malignancies: promoter hypermethylation silences GPX3 expression in hepatocellular carcinoma, lung cancer, and chronic myeloid leukemia, facilitating tumor progression." (PMID 40276677, 2025). "GPX3 inhibited lung cancer cell proliferation by regulating redox-mediated signals." (PMID 37689745, 2023). "Here, we identify the mechanism by which GPx3 inhibits proliferation of lung cancer cells." (PMID 30260967, 2018). "Therefore, to examine the antioxidant-mediated tumor suppressive function of GPx3, we subjected lung cancer cells to serum starvation, which stimulates ROS production without the need for oxidant treatment." (PMID 30260967, 2018). "Thus, this study demonstrates for the first time that the GPx3 suppresses proliferation of lung cancer cells by modulating redox-mediated signals." (PMID 30260967, 2018). "Therefore, we examined the influence of GPx3 on Erk expression and activation (phosphorylation) in lung cancer cells subjected to oxidative stress." (PMID 30260967, 2018). "Thus, this is the first study to show that a GPx3-mediated redox signaling pathway suppresses proliferation of lung cancer cells." (PMID 30260967, 2018). "For example, we recently reported the up-regulation of GPx3 via GR activation in lung cancer cells." (PMID 30260967, 2018). "Moreover, the relationship between GPX3 and miR-324-5p has already been reported in lung cancer." (PMID 32782436, 2020). "Therefore, serum GPx3 change after surgery may be a useful predictive biomarker for recurrence in lung cancer." (PMID 33255360, 2020). "Therefore, serum GPx3 changes after surgery may be useful predictive biomarkers for recurrence in lung cancer." (PMID 33255360, 2020).
lung carcinoma (continued). "We asked whether altered GPx3 expression is a common occurrence in lung cancer cell lines." (PMID 30260967, 2018). "Furthermore, CISD2 mediated ROS-EGR1-PTEN-AKT signaling causes EMT inhibition in lung cancer cells; however, the authors did not explain the underlying mechanism, although they did show that GPx3 overexpression inhibits cell growth." (PMID 30260967, 2018). "Therefore, we next asked whether GPx3 expression impacts ROS levels in lung cancer cells after serum starvation." (PMID 30260967, 2018). "We hypothesized that silencing GPx3 would induce tumorigenesis in lung cancer cells." (PMID 30260967, 2018). "Through q-RT-PCR analysis, we found six genes (DDR1, HSP90B1, SDC1, RPSA, ERGIC3, and LPCAT1) significantly up-regulated and two genes (GPX3 and TIMP3) significantly down-regulated in the lung cancer tissues." (PMID 23374247, 2013). "According to the data on this web site, the expression levels of GPx3 in lung cancer and adjacent normal tissue are Not-detected (level 1) and Low (level 2), respectively." (PMID 28837649, 2017).
diabetes (19 papers, 2008 to 2025). "GPx3 has also been linked to cancer, diabetes, adipocyte differentiation, inflammation, and mortality." (PMID 39765894, 2024). "In the placebo group, low GPx3 activity significantly increased the risk ratio of CV mortality (HR: 1.95, p = 0.008) besides diabetes (HR:1.69, p = 0.04)." (PMID 39765894, 2024). "An inverse association between GPx3 and oxLDL was found, even after adjusting for sex, age, diabetes mellitus (DM) diagnosis, and body mass index (BMI) (β −0.298, p = 0.008)." (PMID 32138220, 2020). "Nevertheless, a significant inverse association between 8-epi PGF2α and GPx3 activity was achieved after adjustment for age, BMI, gender and diabetes (B − 1.082, IC 95 % − 2.081;−0.084, β − 0.234, p = 0.034)." (PMID 26022214, 2015). "Abnormal GPx3 expression may lead to the accumulation of local reactive oxygen species in adipose tissue and increase the risk of diabetes." (PMID 37145256, 2024). "GPx-3 activity may play a key protective role in reducing the risk of cardio-renal disease, which may be compromised in menopausal women with diabetes." (PMID 31817851, 2019). "The effect sizes and p-values were similar between the univariable and full multivariable models for mean arterial pressure, smoking, HbA1c, diabetes duration, GPx-3 activity, sex, and ln (8-OHdG/creatinine ratio) in both ethnic groups." (PMID 40722962, 2025). "Blood glucose, FSH, and GPX3 emerge as the primary drivers of separation along the F1 axis, positioning the L2 group (untreated diabetes) distinctly to the left, highlighting its metabolic and oxidative imbalance." (PMID 40299518, 2025). "Integrative analysis of multiple diabetes genome anatomy project datasets identified GPX3 as one of the most differentially expressed genes." (PMID 38927092, 2024). "This study is the first report to provide good evidence that GPx-3 activity is determined by sex and central obesity in a well-matched population in age and diabetes duration." (PMID 31817851, 2019). "An inverse association between GPx3 and oxidized LDL levels was observed after supplementation with GBN by simple model (β -0.232, p = 0.032) and after adjustment for gender, age, diabetes and BMI (β -0.298, p = 0.008)." (PMID 26022214, 2015). "Our observed increase in Gpx3 within the diabetic endothelium parallels increased Gpx3 within heart observed in a nearly identical model of streptozotocin-induced diabetes in mice." (PMID 18423039, 2008). "GPX3 (glutathione peroxidase 3) and TGF-β1 (transforming growth factor-beta 1) were selected as biomarkers related to oxidative stress regulation and inflammation, both of which are closely linked to metabolic dysfunction and diabetes progression." (PMID 40299518, 2025). "Moreover, GPx3 has garnered considerable attention due to its involvement in various pathological conditions, including diabetes, cardiovascular diseases, and cancer." (PMID 38791447, 2024). "Furthermore, an inverse relationship exists between GPX3 activity and the rate of eGFR decrease in patients with diabetes and advanced CKD." (PMID 38927092, 2024). "GPx3 expression reduces extracellular H2O2 concentration in human muscle cells regulating H2O2 levels and its function as a second messenger, and the inhibition of GPx3 is associated with unbalance in the redox system, insulin resistance and diabetes mellitus." (PMID 35205224, 2022). "Besides, GPx-3 activity seems to have an opposite correlation with the decline of glomerular filtration rate in diabetes and advanced CKD patients." (PMID 39282151, 2022). "Finally, GPx-3 was associated with hypertension, CVD, and diabetes as well as two pathogenesis processes, oxidative stress and apoptosis." (PMID 32466277, 2020). "However, little is known regarding the role of GPx3 in carotid atherosclerosis, which is ubiquitously observed in type 2 diabetes mellitus (T2DM)." (PMID 32862561, 2020).